CRP (C-reactive protein)
Diseases named in the same sentence as CRP in open-access papers (continued):
Sharing a sentence is not in itself a finding about the gene and the disease.
diabetes (continued). "A single IL-6 or a combination of CRP-IL-6 and CRP-fibrinogen plays an important role in the prediction of diabetes, and the main reason for the increase in inflammatory markers may be obesity, through which diabetes risk increases." (PMID 39325793, 2024). "In addition to hypertension, there are other cardiometabolic risk factors (CRFs) such as visceral adiposity, dyslipidemia, insulin resistance, diabetes, elevated levels of fibrinogen and C-reactive protein, and others, all of which increase the risk of CVD events." (PMID 39065815, 2024). "Also, several prospective studies have shown that individuals with higher CRP levels have higher risk of incident type 2 diabetes, indicating that low-grade inflammation may be a cause of diabetes." (PMID 38730445, 2024). "Type two diabetes mellitus is characterized by a chronic inflammation status, and the production of CRP may be triggered by many metabolic and inflammatory factors associated with the development of diabetes mellitus, such as increased blood glucose, adipokines, and free fatty acid levels." (PMID 38673472, 2024). "However, previous research has shown an association between glycaemic control and systemic inflammation in people with diabetes, with increasing levels of haemoglobin A1c (HbA1c) being significantly associated with elevated CRP levels after adjusting for covariates." (PMID 37685924, 2023). "However, after adjustment for confounders (age, sex, body height, heart rate, mean arterial pressure, antihypertensive drugs, left ventricular ejection fraction, atrial fibrillation, diabetes mellitus, cholesterol, creatinine and C-reactive protein), only LVMI and LVWT remained associated with AIx." (PMID 35581324, 2023). "However, if meta-analyses of RCTs are restricted to populations with specific diseases, such as diabetes, abnormal glucose homeostasis, and psychiatric disorders, statistically significant inverse associations between vitamin D supplementation and CRP were observed." (PMID 37340242, 2023). "Epidemiological data report elevated serum levels of inflammatory markers (e.g. IL-6) and C-reactive protein (CRP) and link these to excess risk of diabetes and cardiovascular events suggesting that that inflammatory process and immune-modulation may explain the higher risk." (PMID 35077485, 2022). "The present findings that three simple measures, high C-reactive protein, lactate dehydrogenase, and presence of diabetes mellitus, can quickly identify those at highest risk for intubation can augment clinical findings in identifying patients that may necessitate intensive care unit admission." (PMID 35274051, 2022). "Obesity and diabetes are both more prevalent among Ghanaian migrants residing in Europe and among Ghanaians residing in urban Ghana than among their rural Ghanaian counterparts and appear to be the main factors attenuating the association between CRP and HTN/BP." (PMID 34478414, 2022). "On the other hand, it has been suggested that CRP levels could be monitored to assess the improvement in CV disease and, if required, to perform interventions that are effective in lowering CRP levels, such as exercise, weight loss, smoking cessation, or diabetes control." (PMID 36614866, 2022). "In addition, studies have shown that inflammatory indicators, such as C-reactive protein and procalcitonin; underlying diseases, such as hypertension, diabetes, and chronic kidney disease; as well as coronary artery disease, are correlated with the occurrence of AKI." (PMID 36505004, 2022). "Other longitudinal studies have suggested elevated IL-6 and CRP levels associated with PD, as significant risk factors for insulin resistance and diabetes mellitus (DM)." (PMID 35629064, 2022). "Although diabetes was adjusted for in model 3, other concomitant inflammatory or neurodegenerative diseases were not adjusted for, which may possibly influence the association between CRP and HTN." (PMID 34478414, 2022).
diabetes (continued). "The association remained significant even after adjustment for traditional CVD risk factors such as age, prior CVD history, diabetes, smoking, triglycerides, total cholesterol, CRP, albumin, hemoglobin, and Apo B. Moreover, Apo A1/Apo B may be used as a predictor of the occurrence of future ACS." (PMID 33913384, 2021). "In addition to valvular calcification, several factors, including age, duration of dialysis, phosphate and/or Ca×P product, oral calcium intake, use of vitamin D, diabetes, C-reactive protein, and low albumin, are generally associated with ectopic calcification." (PMID 34640403, 2021). "The inverse association of albumin with hs-CRP is consistent with the anti-inflammatory properties of albumin and its consumption with chronic inflammation, that may complicate the clinical course of diabetes." (PMID 34239442, 2021). "Moreover, elevated CRP levels are associated with increased risk of incident disease, such as diabetes and cardiovascular disease, and mortality, and CRP has been recommended as an adjunct screening tool for cardiovascular risk prediction in the general population." (PMID 34925360, 2021). "Additionally, OPN with other reported inflammatory cytokines particularly IL-6, IL-8, IL-18, IL-1β, TNF-α, and serum CRP have been implicated in hypertension associated with diabetes via mediating the vascular effects of both angiotensin II (Ang II) and aldosterone, respectively." (PMID 34917685, 2021). "In addition, diabetes was found to be associated with increased inflammation within AS valves, as demonstrated by increased C-reactive protein (CRP) expression, which may contribute to faster AS progression." (PMID 33255639, 2020). "Therefore, the aim of this study was to prospectively evaluate the association between the CRP trajectory during 2013–2015 and subsequent risk of diabetes, as assessed by both fasting blood glucose (FBG) and glycated hemoglobin A1c (HbA1c), in approximately 6300 Chinese adults." (PMID 32612667, 2020). "The association of Metrnl with hs‐CRP (r = −0.141; P = 0.009), IL‐1β (r = −0.240; P = 0.002), and IL‐11 (r = 0.178; P = 0.025) remained statistically significant even after adjustments for age, sex, smoking, alcohol intake, diabetes, BMI, Cr, FBG, TC, TG, and LDL‐C." (PMID 30394666, 2019). "Moreover, overweight was consistently associated with hypertension, hs-CRP, and diabetes." (PMID 31469876, 2019). "C-reactive protein (CRP) is an acute-phase inflammatory protein synthesized in the liver through the stimulation of interleukin-6 that has been extensively studied as a marker of the subclinical inflammation associated with obesity, metabolic syndrome, diabetes and cardiovascular disease." (PMID 30205424, 2018). "Similarly, we also found that diabetes duration, HbA1c, and Hs-CRP, were associated with DR." (PMID 30135138, 2018). "Furthermore, the inconsistent and modest associations of CRP polymorphisms with diabetes and glucose levels observed in previous and current studies could be due to insufficient sample size." (PMID 28801571, 2017). "It has been reported that CRP could increase the risk of diabetes." (PMID 29404372, 2017). "Regarding diabetes, a meta-analysis with 16 studies found an association between hs-CRP and incident diabetes although a nested case-control study in the European Prospective Investigation of Cancer (EPIC)-Norfolk cohort suggested that this association might be confounded by central adiposity." (PMID 27527152, 2016). "Additionally, clinical data for estimated glomerular filtration rate (eGFR), diabetes, hypertension, heart failure, underlying chronic kidney disease, C-reactive protein (CRP), mean arterial pressure, and hemoglobin for these patients were not collected in this study." (PMID 27689992, 2016).
diabetes (continued). "Issues that reduce the inflammation (particularly, key inflammatory markers such as pro-inflammatory mediators TNFα, IL-6, IL-1β and CRP) could offer a vital public health tool to reduce the burden of diabetes and associated complications including cardiovascular diseases in the general population." (PMID 27527213, 2016). "This risk is further increased in the presence of elevated CRP and low serum albumin as well as high HbA1c level at the onset of dialysis in agreement with recent reports, suggesting that acute phase reactants and poor control of diabetes worsen the prognosis further." (PMID 27529033, 2016). "Association between aspirin and lower all-cause mortality was limited to patients with age ≥65 years, diabetes, hypertension, decreased renal function, and higher levels of coronary artery calcium score, low-density lipoprotein cholesterol and high-sensitivity C-reactive protein." (PMID 26035823, 2015). "In addition, HBP and diabetes were associated with intermediate CRP levels." (PMID 26703686, 2015). "Risk of metabolic syndrome, hyperglycaemia and diabetes, and elevated high-sensitivity CRP may be affected by childhood BMI and skinfold thickness, while risk of hypertension, raised triglycerides and reduced HDL cholesterol is associated more strongly with BMI gain from childhood to adulthood." (PMID 25880559, 2015). "Furthermore, hs-CRP and increased fibrinogen levels are independent risk factors for coronary heart disease, and a number of studies have reported elevated fibrinogen levels in patients with diabetes." (PMID 26273677, 2015). "However, this correlation was explained by age, presence of diabetes, and CRP levels, suggesting that underlying inflammation may well be an important confounder of this relationship and may mediate abnormalities in both parameters." (PMID 24356038, 2014). "We aimed to examine the prevalence of and modifiable factors associated with elevated C-reactive Protein (CRP), a marker of inflammation, in men and women with newly diagnosed Type 2 Diabetes mellitus (DM) in a population-based setting." (PMID 25163828, 2014). "In the unadjusted model (Model 1) and after progressive adjustment for age, gender, hypertension, diabetes, glomerular filtration rate, body fat percentage, and use of statins (Models 2 to 4), the highest tertile of zinc presented a direct association with higher CRP." (PMID 26676114, 2014). "The elevated level of inflammatory markers such as CRP or fibrinogen at the beginning of stroke may reflect the burden of atherosclerosis and/or the presence of concomitant risk factors (e.g., hypertension, diabetes mellitus, obesity)." (PMID 24531853, 2014). "Thus, supported by a large number of observational studies and meta-analyses, CRP is considered as a mediator of cardiovascular disease, independently of age, smoking, cholesterol levels, blood pressure, and diabetes among others traditional risk factors evaluated in the clinical setting." (PMID 23690772, 2013). "In a prospective study from February 2009 to February 2012, we assessed diabetes mellitus (DM) status, clinical and PD-associated characteristics, medication use, CRP levels, components of MetS, and VFA in 183 PD patients." (PMID 23758640, 2013). "In addition to Hp; other possible genetic polymorphisms like CRP may have its effect on diabetes through different mechanisms." (PMID 23283045, 2012). "Further studies could combine novel methods for survival analysis with longitudinal assessment of biomarkers such as C- reactive protein or markers of oxidative stress to better understand the strong association of diabetes with an increasing risk of death in prevalent hemodialysis patients." (PMID 23025844, 2012). "Considering the high serum levels of CRP in these cases, the inflammation noted in liver cells could be considered as the underlying cause of insulin resistance, impaired glucose tolerance and diabetes in these patients." (PMID 23497547, 2012).
diabetes (continued). "However, six weeks of exercise improved ACh-mediated vasodilatation while also reducing plasma CRP levels in db/db mice; this was associated with a significant correlation between plasma CRP levels and body weight, a finding that is consistent with other reports in experimental and human diabetes." (PMID 20847810, 2010). "Therefore, the authors argued that variation in genes including HNF1A may have subsequent impact on vascular disease and diabetes risk that is influenced or marked by circulating CRP concentrations." (PMID 20716378, 2010). "HNF1A might therefore have an impact on vascular disease and diabetes risk that is mediated by CRP." (PMID 20716378, 2010). "Low levels of CRP have been shown for a number of autoimmune diseases, and with the predicted low levels of circulating CRP in the Fulani groups, it could be assumed that the Fulani may be more susceptible to autoimmune diseases, and this is true for some disorders, e.g. diabetes." (PMID 19545442, 2009). "Also, the distribution of cardiovascular risk factors such as smoking status and history of diabetes were different between the men and women, and may have mediated influences through CRP." (PMID 18167554, 2008). "Associationsbetween PM2.5 and CRP were consistently, and often significantly, elevated among the 8 individualswith diabetes (26 repeated samples), 14 individuals withobesity (41 repeated samples), and 4 individuals with concurrent diabetes, obesity, andhypertension (14 repeated samples)." (PMID 16835049, 2006). "The p values of data being 0.000, 0.000, 0003, and 0.002 when the relationship between diabetes duration/HbA1c/urine albumin/CRP levels and the prevalence of diabetes were assessed, respectively." (PMID 41541002, 2026). "Major predictors included advanced age (HR 6.84), hypertension (HR 2.70), hypoalbuminemia (HR 2.64), elevated CRP (HR 1.38), and diabetes (HR 1.29)." (PMID 41743061, 2026). "The study found significant correlation between the prevalence for DR and the duration of diabetes, HbA1c, CRP and urine albumin levels." (PMID 41541002, 2026). "Median CRP values were higher in early (0-4 years: 0.62 mg/L) and long-standing diabetes (≥15 years: 0.77 mg/L) compared with intermediate-duration groups (p = 0.063)." (PMID 41893351, 2026). "The risk of developing CAV is further elevated by modifiable factors, including smoking, hypertension, diabetes mellitus, dyslipidemia, and elevated high-sensitivity C-reactive protein (hs-CRP) levels." (PMID 41523716, 2026). "Our research has shown a significant association between the prevalence of DR and elevated levels of HbA1c, CRP, and urinary albumin and duration of diabetes." (PMID 41541002, 2026). "Changes were analyzed using generalized estimating equation models adjusted for antiplatelet therapy, diabetes mellitus, smoking, and C-reactive protein (CRP)." (PMID 42194683, 2026). "In the short term, RYGB was associated with greater improvements in lipid profile, glycemic control, and C-reactive protein, as well as higher remission rates of type 2 diabetes mellitus and dyslipidemia." (PMID 42053904, 2026). "Patients were older than controls and had more risk factors for stroke, as reflected by their hypertension, dyslipidemia, and diabetes, as well as higher waist–hip ratio, C-reactive protein (CRP) and leukocyte counts." (PMID 41536544, 2026). "The composite C-reactive protein-triglyceride glucose (CRP-TyG) index integrates inflammatory and metabolic dimensions and may therefore provide a more informative marker for cancer risk stratification than either component alone, particularly in hospitalized patients with diabetes." (PMID 42232548, 2026). "Higher dNLR quartiles were correlated with improved metabolic profiles: lower CRP (median Q4: 0.2 vs Q1: 0.3; P < .001), reduced HbA1c (Q4: 5.7 ± 1.0% vs Q1: 5.9 ± 1.2%; P = .002), and decreased hypertension/diabetes prevalence (both P < .05)." (PMID 41496140, 2026).
diabetes (continued). "We found a significant association between the CRP/HDL-c ratio and the risk of hyperuricemia in people with diabetes or prediabetes." (PMID 40655403, 2025). "This study identified age, limb dysfunction, diabetes, tube feeding, BMI, NIHSS score and C-reactive protein as independent risk factors for SRS." (PMID 39979762, 2025). "As the CTI quartile increases, several clinical characteristics show significant changes, particularly in hypertension, diabetes, and CRP levels." (PMID 41343565, 2025). "The synergistic relationship between periodontitis and diabetes mellitus in elevating hs-CRP levels provides compelling evidence for integrated treatment approaches that address both conditions simultaneously." (PMID 41153725, 2025). "Cox regression models were adjusted for age, sex, estimated glomerular filtration rate, diabetes, coronary artery disease, heart failure, hypertension, atrial fibrillation, C-reactive protein, and low-density lipoprotein cholesterol." (PMID 40749516, 2025). "This pattern emphasizes the importance of accounting for clinical covariates such as BMI, diabetes status, HbA1c, and smoking, each of which independently correlated with elevated CRP levels in our analysis." (PMID 41001317, 2025). "The linear regression was adjusted for age, gender, ethnicity, smoking status, alcohol consumption, hypertension, diabetes, BMI, waist circumference, Ghb, CRP, ALB, CR, WBC, RBC, and HGB." (PMID 40271127, 2025). "In this retrospective cohort study, we investigate the association between CRP levels and the severity of DFI in patients with diabetes." (PMID 40373091, 2025). "Other independent predictors for all-cause mortality in FDAF patients were age, diabetes mellitus, prior cancer, moderate and severely abnormal LVEF, eGRF < 60 ml/min and c-reactive protein > 5 mg/L." (PMID 40033211, 2025). "Diabetes additionally emerged as a notable contributor to adverse outcomes, correlating with elevated CRP levels, more ICU admissions, and longer inpatient stays." (PMID 40431302, 2025). "The results showed that diabetes, decreased hemoglobin level, increased serum PAF and IL-17 levels, CRP were the independent risk factors for intestinal obstruction in patients with radiation enteritis (p < 0.05)." (PMID 40823570, 2025). "The general clinical variables assessed were body mass index (BMI), present or past clinical hypermobility, main clinical comorbidities (diabetes, dyslipidaemia, sleep apnea, smoking), menopause and C-reactive protein (CRP) and sedimentation rate (SR)." (PMID 40290489, 2025). "A feedback loop that prolongs metabolic dysfunction and makes managing diabetes more difficult is created when proinflammatory cytokines like IL-6 and CRP exacerbate insulin resistance." (PMID 40407432, 2025). "Univariate analysis identified nine potentially significant indicators: age, diabetes type, blood glucose, cortisol, serum bicarbonate, leukocyte, neutrophil, CRP, and procalcitonin (p<0.05)." (PMID 39946377, 2025). "The risk of sepsis following post-COVID HZ was significantly elevated among individuals with hypertension, diabetes mellitus, alcohol use, COPD, vitamin D deficiency, impaired renal function, elevated CRP, and age ≥ 50 years." (PMID 40722700, 2025). "This study demonstrates that a composite assessment of first-trimester biochemical markers - CRP, uric acid, and PPBS - alongside key clinical risk factors such as PCOS and family history of diabetes, provides robust predictive accuracy for GDM." (PMID 41200603, 2025). "Research has shown elevated serum levels of IL-6 and TNF-α in both diabetes and obesity, with IL-6 and C-reactive protein (CRP) levels predicting the future onset of type 2 diabetes." (PMID 39852378, 2025). "Recent studies also showed that SGLT2i had anti-inflammatory effects in patients with type 2 diabetes mellitus, reducing not only CRP levels but also TNF-α and IL-6." (PMID 40134442, 2025).